SMPD4 (sphingomyelin phosphodiesterase 4)
Description:
Catalyzes the hydrolysis of membrane sphingomyelin to form phosphorylcholine and ceramide. It has a relevant role in the homeostasis of membrane sphingolipids, thereby influencing membrane integrity, and endoplasmic reticulum organization and function. May sensitize cells to DNA damage-induced apoptosis. In skeletal muscle, mediates TNF-stimulated oxidant production (By similarity).
Synonyms: nSMase-3; nSMase3; KIAA1418; SKNY; FLJ20297; FLJ20756; NET13; NEDMABA; NEDMEBA
Tractability: Antibody: UniProt places it where antibodies can reach, with medium confidence; UniProt predicts a signal peptide or a membrane-spanning region; its Gene Ontology location is reachable by antibodies, with medium confidence. PROTAC: ubiquitination databases record sites on it; its protein half-life has been measured.
Target class: Enzyme; Hydrolase
Gene: Protein-coding gene on chromosome 2 (130,151,392 to 130,183,901, reverse strand). Ensembl gene ENSG00000136699.
Subcellular location: Endoplasmic reticulum membrane; Golgi apparatus membrane; Nucleus envelope; Cell membrane, sarcolemma
Subcellular location (Human Protein Atlas): Nuclear membrane; Cytosol
Pathways (Reactome):
Metabolism: Glycosphingolipid catabolism
Gene Ontology:
Molecular function: sphingomyelin phosphodiesterase activity; sphingomyelin phosphodiesterase D activity
Biological process: cellular response to tumor necrosis factor; ceramide biosynthetic process; endoplasmic reticulum organization; glycerophospholipid catabolic process; sphingomyelin catabolic process
Cellular component: endoplasmic reticulum; endoplasmic reticulum membrane; Golgi apparatus; Golgi membrane; nuclear envelope; nuclear outer membrane; trans-Golgi network; sarcolemma
Genetic constraint (gnomAD): Loss-of-function variants: 56 observed, 90.95 expected, observed/expected ratio (o/e) 0.62, 90% interval 0.5 to 0.77. The upper end of that interval is the gene's LOEUF score, 0.77, which puts it in group 3 of 6, group 1 being the genes least tolerant of losing a copy. Missense variants: 823 observed, 1,025.8 expected, observed/expected ratio (o/e) 0.8, 90% interval 0.76 to 0.85. Synonymous variants: 382 observed, 424.2 expected, observed/expected ratio (o/e) 0.9, 90% interval 0.83 to 0.98.
Homologues: Orthologues: macaque SMPD4 (99% identical), chimpanzee SMPD4 (97% identical), rabbit SMPD4 (91% identical), guinea pig SMPD4 (91% identical), rat Smpd4 (90% identical), mouse Smpd4 (90% identical), pig SMPD4 (89% identical), dog SMPD4 (89% identical), tropical clawed frog smpd4 (66% identical), zebrafish smpd4 (61% identical), Drosophila melanogaster CG6962 (24% identical), Caenorhabditis elegans R05D11.9 (17% identical).
Diseases named in the same sentence as SMPD4 in open-access papers:
SMPD4 is named in the same sentence as 32 diseases in open-access papers, as found by Europe PMC text mining. Sharing a sentence is not in itself a finding about the gene and the disease. The quoted sentences say what the papers report.
microcephaly (13 papers, 2020 to 2025). A congenital or acquired developmental disorder in which the circumference of the head is smaller than normal for the person's age and sex. "We propose a combination of these mechanisms to explain the microcephaly seen in individuals with SMPD4 deficiency." (PMID 39470011, 2024). "The biallelic loss-of-function variants of SMPD4 have been identified in a group of children with neurodevelopmental disorder with microcephaly, arthrogryposis, and structural brain anomalies (NEDMABA)." (PMID 35651939, 2022). "SMPD4 is a neutral sphingomyelinase with poorly characterized enzymatic activity, which was found mutated in a specific form of congenital microcephaly." (PMID 35203325, 2022). "In contrast, SMPD4 deficiency has recently been linked to microcephaly and cellular division defects." (PMID 35203325, 2022). "Loss-of-function SMPD4 variants are linked to microcephaly in humans." (PMID 41214365, 2025). "As an example of the application of this genetic toolkit, our findings with dSMPD4KO flies offer insights into how SPL metabolism orchestrated by the SMases contributes to brain functions, shedding light on the mechanisms underlying SMPD4-associated microcephaly." (PMID 41214365, 2025). "As a proof-of-principle application, we demonstrated the cellular requirements for CerPE regulation in vivo by characterizing the CG6962 gene (hereafter dSMPD4), a putative ortholog of the human neutral sphingomyelinase gene SMPD4 that is associated with microcephaly." (PMID 41214365, 2025). "A recent study identified five individuals from three unrelated families with biallelic loss-of-function SMPD4 variants who had insulin-dependent diabetes and a severe neurodevelopmental disorder and microcephaly, while hearing impairment was observed in 2/5 individuals." (PMID 41191133, 2025). "Because humans with SMPD4 deficiency have microcephaly, we hypothesized there is either a compensatory mechanism in mouse, or that human neurodevelopmental differences explain this disparity." (PMID 39470011, 2024). "SMPD4 is a neutral sphingomyelinase implicated in a specific type of congenital microcephaly." (PMID 35203325, 2022). "The defects of SMPD4 can lead to a neurodevelopmental disorder characterized by microcephaly and structural brain anomalies." (PMID 38045239, 2024). "We present a mouse model of loss of Smpd4 that recapitulates human cerebellar hypoplasia but not microcephaly." (PMID 39470011, 2024). "The loss of function of SMPD4 will induce endoplasmic reticulum (ER) stress, autophagy, impaired sphingolipids homeostasis, cell cycle dysregulation, and this could partially explain the severe growth failure and microcephaly in SMPD4-related disorder." (PMID 36926587, 2023). "This binding might play an important role in the development of microcephaly, as inactivation of ANKLE2 and loss of SMPD4, which encodes a neutral sphingomyelinase that produces ceramide in the ER, all leads to development of the disease." (PMID 34793833, 2021). "In addition, fibroblasts derived from SMPD4 patients suffering from a developmental disorder characterized by microcephaly and congenital arthrogryposis show ER abnormalities and are more prone to apoptosis under stress conditions." (PMID 33563298, 2021). "Genetic defects with Smpd4 inheritance present cognitive problems, defects in brain development, and microcephaly, thus further studies may illuminate a relationship between neurotropic infections and such disease outcomes." (PMID 33370419, 2020). "Given our finding that conditional Smpd4 loss in the mouse forebrain does not lead to microcephaly as in humans, we hypothesized that neutral sphingomyelinase genes could act redundantly in the mouse." (PMID 39470011, 2024).
microcephaly (continued). "Variants in multiple genes regulating endosomal trafficking and/or fusion of secretory vesicles [such as SMPD4, WDFY3, TRAPPC4, RAB18, VPS13B, EXOC7, EXOC8, VPS11], have been associated with the occurrence of microcephaly, cerebral atrophy, and neurodevelopmental delay." (PMID 36538041, 2023). "Smpd4 null and forebrain-specific knockout mice do not exhibit the microcephaly seen in human patients." (PMID 39470011, 2024). "We hypothesized that the lack of microcephaly in the Smpd4 forebrain conditional KO mice could be due to Smpd3 compensatory sphingomyelinase activity in the mouse forebrain." (PMID 39470011, 2024). "Additionally, forebrain-specific deletion of SMPD4 did not lead to microcephaly." (PMID 39470011, 2024).
breast carcinoma (3 papers, 2018 to 2023). "The expression of DGAT1, DUT, LYPLA1, and POLR2K was linked to an increased risk of breast cancer, whereas SMPD4 was associated with a protective effect." (PMID 37644433, 2023). "We found that SMPD2, SMPD4, and SMPD5 were significantly higher in breast cancer tissue than that in paired normal breast tissue, while SGMS2 was significantly decreased in breast cancer tissue (TCGA cohort, n=112)." (PMID 29731990, 2018).
arthrogryposis (2 papers, 2022 to 2023). A rare, non-progressive congenital disorder characterized by multiple joint contractures which are present at birth. "A pathogenic splicing variant in SMPD4 in trans with a deletion of 59.72 kb (chr2: 130,142,742–130,202,459) spanning SMPD4 was found in a fetus with arthrogryposis (case 2014) using WES-based CNV analysis." (PMID 37880672, 2023).
bladder cancer (1 paper, 2021). "In this study, we found that SMPD4 was hypermethylated and upregulated in bladder cancer tissues in comparison to normal adjacent tissues, and a low expression of SMPD4 showed a tendency to associate with worse overall survival in bladder cancer patients." (PMID 34868913, 2021). "We found that a low expression of METTL14 (a m6A methyltransferase), SMPD4, and SGK2, but a high expression of ALKBH5 (a m6A de methyltransferase), LINC00482, and HIPK3, showed a tendency to associate with worse overall survival in bladder cancer patients." (PMID 34868913, 2021). "For example, SMPD4 was overexpressed in the late stage of clear cell renal cancer and acted as a biomarker for discriminating early and late stages of ccRCC, but its function in bladder cancer is unclear." (PMID 34868913, 2021). "We found that the m6A peak was enriched around the 5′UTR of SMPD4 in the tumor group of bladder cancer not in adjacent normal tissues." (PMID 34868913, 2021).
clear cell renal carcinoma (1 paper, 2021). A malignant epithelial neoplasm of the kidney characterized by the presence of lipid-containing clear cells within a vascular network. "For instance, sphingomyelin phosphodiesterase 4 (SMPD4) was overexpressed in the late stage of clear cell renal cancer and acted as a biomarker for discriminating the early and late stages of ccRCC." (PMID 34868913, 2021).
Ebola (1 paper, 2020). "A future analysis of the antiviral role of SMPD4 includes testing the effects of the widely used statins, drugs that reduce cholesterol, on the spread of PRV or other neurotropic viruses as it has been shown for Ebola." (PMID 33370419, 2020).
Failure to thrive (1 paper, 2024). Failure to thrive (FTT) refers to a child whose physical growth is substantially below the norm. "We present an Smpd4 null mouse model with incompletely penetrant perinatal lethality, failure to thrive and cerebellar hypoplasia." (PMID 39470011, 2024).
hepatocellular carcinoma (1 paper, 2023). A malignant tumor that arises from hepatocytes. "SMPD4 was also found to be a lipid metabolism-related gene associated with hepatocellular carcinoma prognosis." (PMID 37644433, 2023).
Hypertension (1 paper, 2023). The presence of chronic increased pressure in the systemic arterial system. "The protein encoded by SMPD4 was a sphingomyelinase involved in sphingolipid metabolism pathway, and mounting evidence pointed toward that a derangement of this pathway might trigger the precursor clinical conditions of hypertension and hypertension itself." (PMID 36869404, 2023).
myeloma (1 paper, 2019). "SMPD2 and SMPD4 overexpression also result in a worse PFS in this myeloma subgroup." (PMID 31756922, 2019).
virus infection (1 paper, 2020). "The identification of SMPD4 interaction with Us9 in both immature and mature neurons suggests a common neuronal response to virus infection that is dependent on membrane composition." (PMID 33370419, 2020).
cancer (3 papers, 2015 to 2023). A tumor composed of atypical neoplastic, often pleomorphic cells that invade other tissues. "Notably, the effect of SM metabolism was investigated by studying neutral SMase 3 (nSMase3), encoded by the SMPD4 gene, which is deregulated in human cancer." (PMID 36983016, 2023).
infection (1 paper, 2020). The state of being infected such as from the introduction of a foreign agent such as serum, vaccine, antigenic substance or organism. "Quantification of capsid association revealed that while 18% of capsids co-localize with GFP-Us9 in wildtype infections, knockdown of SMPD4 increased capsid-Us9 association to 88%." (PMID 33370419, 2020). "In wildtype infection, SMPD4 colocalizes with capsids and may reduce capsid association with Us9, which is required for anterograde spread." (PMID 33370419, 2020). "However, interestingly, infection with Us9-deleted virus (Us9null) did not express the same levels of SMPD4 or LC3, which further supports a function between Us9 and neuronal stress-response." (PMID 33370419, 2020). "Upon infection, some mRFP-VP26 capsids colocalized with SMPD4 foci but not GFP-Us9 (arrow)." (PMID 33370419, 2020). "While an increase in SMPD4 protein abundance during Us9WT and Us9YY infections correlated with an increase in LC3 levels, a marker of cellular stress and autophagy, it is possible that these are two independent responses to infection rather than a functional interaction." (PMID 33370419, 2020).
neurological disease (1 paper, 2024). "Notably, many of these DEGs have been associated previously with neurological disease including SPHK2 (sphingosine kinase 2); P2RX7 (purinergic receptor P2X 7); SMPD4 (sphingomyelin phosphodiesterase 4); ASAH1 (N-acylsphingosine amidohydrolase 1)." (PMID 38625017, 2024).
SMPD4 also shares sentences with these, for which no sentence is quoted: neurodevelopmental disorder (4 papers); tumor (2); Cerebral atrophy (1); developmental delay (1); fibromuscular dysplasia (1); Hearing impairment (1); Holt-Oram syndrome (1); Hyporeflexia (1); insulin-dependent diabetes (1); keratoconus (1); macular degeneration (1); muscular dystrophy (1); neurodegenerative disease (1); Neurodevelopmental delay (1); paraplegia (1); retinopathy (1); spinal muscular atrophy (1); thyrotoxicosis (1).